USP34 (ubiquitin specific peptidase 34)
Description:
Ubiquitin hydrolase that can remove conjugated ubiquitin from AXIN1 and AXIN2, thereby acting as a regulator of Wnt signaling pathway. Acts as an activator of the Wnt signaling pathway downstream of the beta-catenin destruction complex by deubiquitinating and stabilizing AXIN1 and AXIN2, leading to promote nuclear accumulation of AXIN1 and AXIN2 and positively regulate beta-catenin (CTNBB1)-mediated transcription. Recognizes and hydrolyzes the peptide bond at the C-terminal Gly of ubiquitin. Involved in the processing of poly-ubiquitin precursors as well as that of ubiquitinated proteins.
Synonyms: KIAA0570; KIAA0729
Tractability: Small molecule: a structure with a bound ligand is known. PROTAC: ubiquitination databases record sites on it; its protein half-life has been measured.
Gene: Protein-coding gene on chromosome 2 (61,187,463 to 61,471,087, reverse strand). Ensembl gene ENSG00000115464.
Subcellular location (Human Protein Atlas): Vesicles
Pathways (Reactome):
Metabolism of proteins: Ub-specific processing proteases
Signal Transduction: TCF dependent signaling in response to WNT
Gene Ontology:
Molecular function: cysteine-type deubiquitinase activity; cysteine-type endopeptidase activity; protein binding
Biological process: positive regulation of canonical Wnt signaling pathway; protein K48-linked deubiquitination; protein deubiquitination; Wnt signaling pathway; post-translational protein modification; regulation of signal transduction
Cellular component: cytosol
Genetic constraint (gnomAD): Loss-of-function variants: 46 observed, 387.45 expected, observed/expected ratio (o/e) 0.12, 90% interval 0.093 to 0.15. The upper end of that interval is the gene's LOEUF score, 0.15, which puts it in group 1 of 6, group 1 being the genes least tolerant of losing a copy. Missense variants: 3,656 observed, 3,985.1 expected, observed/expected ratio (o/e) 0.92, 90% interval 0.89 to 0.94. Synonymous variants: 1,520 observed, 1,342.8 expected, observed/expected ratio (o/e) 1.13, 90% interval 1.08 to 1.18.
Gene-disease validity (ClinGen):
ClinGen rates the evidence that USP34 causes each of these diseases.
congenital heart disease (autosomal dominant): Limited. A heart disease that is present at birth.
Homologues: Orthologues: chimpanzee USP34 (99% identical), macaque USP34 (99% identical), dog USP34 (99% identical), rabbit USP34 (98% identical), pig USP34 (98% identical), mouse Usp34 (98% identical), rat Usp34 (97% identical), guinea pig USP34 (96% identical), tropical clawed frog usp34 (91% identical), zebrafish USP34 (67% identical). Paralogues in human: USP38 (6% identical), USP9X (6% identical), USP9Y (6% identical), USP24 (6% identical), USP35 (6% identical), USP31 (5% identical), USP36 (5% identical), USP32 (5% identical), USP47 (4% identical), USP43 (4% identical), USP8 (4% identical), USP42 (4% identical), and 59 more.
Diseases named in the same sentence as USP34 in open-access papers:
USP34 is named in the same sentence as 48 diseases in open-access papers, as found by Europe PMC text mining. Sharing a sentence is not in itself a finding about the gene and the disease. The quoted sentences say what the papers report.
glioma (6 papers, 2021 to 2025). A benign or malignant brain and spinal cord tumor that arises from glial cells (astrocytes, oligodendrocytes, ependymal cells). "For example, in glioma stem cells, it was found that ubiquitin specific peptidase 34 (USP34) regulated glioma stem cell progression by directly heterodimerizing UBE2I and regulating the aberrant expression of Pin1 at the post-translational level." (PMID 40025314, 2025). "The work of Pan et al29 suggests that knocking down USP34 in gliomas increases the level of FOXC1 ubiquitination and decreases its protein expression level." (PMID 40260316, 2025). "USP1 in glioma, as well as USP7 and USP34, also converge on EZH2 to promote tumorigenesiss." (PMID 37892185, 2023).
pancreatic cancer (5 papers, 2022 to 2025). "-15 Additionally, Gu et al16 found that USP34 can regulate the survival of human pancreatic cancer cells, which is a potential therapeutic target for treating human pancreatic cancer." (PMID 40260316, 2025). "Pancreatic cancer cell proliferation and migration are promoted by USP34 overexpression via upregulation of the Akt protein, and pancreatic cancer cell apoptosis induced by an Akt inhibitor is reversed by USP34 overexpression." (PMID 37664545, 2023). "USP34 can also promote the proliferation and migration of pancreatic cancer cells by upregulating p-AKT and p-PKC proteins." (PMID 37409345, 2023). "USP34 facilitated pancreatic cancer cell progression targeting PRR11." (PMID 36551227, 2022). "Notably, further exploration of treating pancreatic cancers revealed that ubiquitin specific protease 34 (USP34) knockdown inhibited proliferation and migration, and induced apoptosis targeting PRR11." (PMID 36551227, 2022).
developmental delay (2 papers, 2021 to 2026). "We report six individuals with heterozygous loss-of-function variants in USP34, including five with confirmed de novo variants, associated with global developmental delay, craniofacial dysmorphism, marked speech impairment, variable autism spectrum disorder, and distal limb anomalies." (PMID 42315110, 2026).
diffuse large B-cell lymphoma (2 papers, 2023). "Research has shown that USP34 overexpression can be detected in diffuse large B cell lymphoma instead of follicular lymphoma, but a significant association has not been identified between the USP34 protein level and patient survival." (PMID 37664545, 2023).
hearing loss (2 papers, 2023 to 2024). "For almost all traits, except IUGR and hearing loss, our analysis pinpointed at least two SROs including the BCL11A, and the USP34 and XPO1 genes, respectively." (PMID 36807877, 2023). "Moreover, patients feature phenotypes, including hearing loss, intrauterine growth restriction, and short stature, that cannot be delineated to variations in the BCL11A gene but are associated with USP34 (ubiquitin specific peptidase 34) and XPO1 (exportin 1), two candidate genes in close proximity." (PMID 38392344, 2024).
laryngeal squamous cell carcinoma (2 papers, 2025). A squamous cell carcinoma that arises from the larynx. "Knockdown of USP34 could significantly inhibit laryngeal squamous cell carcinoma (LSCC) cell growth, but overexpression of SOX2 could reverse this effect." (PMID 40599863, 2025).
polycystic ovary syndrome (2 papers, 2015 to 2023). A disorder that manifests as multiple cysts on the ovaries. "The third target gene, USP34 PMID:25975428, has an association with polycystic ovary syndrome." (PMID 38283897, 2023).
prostate carcinoma (2 papers, 2019 to 2021). A carcinoma that arises from epithelial cells of the prostate gland. "As a result, the high expression of the USP34 has a protective effect on prostate cancer recurrence in TCGA and GEO gene expression profile, and the gene NDUFA13, UQCR11 is the opposite." (PMID 31795990, 2019). "So, further we expect that Low-dose lymphocyte immunotherapy might be an effective therapy for prostate cancer, and even NDUFA13, UQCR11, and USP34 might be immunocheckpoints like PD-1/ PD-L1, they may play its role through Th2 and Tcm cells." (PMID 31795990, 2019). "We finally screened three genes related to prostate cancer recurrence: NDUFA13, UQCR11, USP34." (PMID 31795990, 2019).
ataxia telangiectasia (1 paper, 2024). Ataxia-telangiectasia is the association of severe combined immunodeficiency (affecting mainly the humoral immune response) with progressive cerebellar ataxia. "In addition, USP34 responds to DNA damage and is a downstream target of mutant ataxia telangiectasia in DNA damage." (PMID 39664521, 2024).
breast carcinoma (1 paper, 2021). "After prognosis analysis, we found four genes (AKT1 (AKT serine/threonine kinase 1), ERBB2 (Erb-B2 receptor tyrosine kinase 2), KMT2C (lysine methyltransferase 2C), and USP34 (ubiquitin specific peptidase 34)) associated with survival of breast cancer." (PMID 34408553, 2021). "After prognosis analysis, we found four genes (AKT1, ERBB2, KMT2C, and USP34) associated with survival of breast cancer." (PMID 34408553, 2021). "Four genes (AKT1, ERBB2, KMT2C, and USP34) were associated with survival of breast cancer." (PMID 34408553, 2021).
cortical dysplasia (1 paper, 2023). "Deletions affecting only the BCL11A gene are not penetrant for hearing loss and IUGR traits, while those uniquely involving the USP34 and XPO1 genes are neither penetrant for cortical dysplasia nor for cerebellar anomalies." (PMID 36807877, 2023).
diabetes mellitus (1 paper, 2023). A metabolic disorder characterized by abnormally high blood sugar levels due to diminished production of insulin or insulin resistance/desensitization. "The GO terms for USP34 indicate a response to oxygen-containing compound and regulation of fat cell differentiation, which are closely related to diabetes mellitus and cardiovascular diseases." (PMID 38283897, 2023). "Ten potential target genes were identified, out of which three common potential target genes (CCDC28b, PDCD6IP, and USP34) were selected, which are most effective for cardiovascular diseases, diabetes mellitus, IBD, and PCOS." (PMID 38283897, 2023).
E. coli infection (1 paper, 2014). "The expression of Defensin C (Def) an additional Imd-dependent antimicrobial peptide encoding gene, was also significantly deregulated in both Usp34-silenced non-infected flies and at 3 hours post-infection but then, it was strongly compromised from 6 to 9 hours following E. coli infection." (PMID 25027767, 2014).
gastric cancer (1 paper, 2026). A primary or metastatic malignant neoplasm involving the stomach. "Transcriptomic analysis demonstrated significant downregulation of DPP6 and DLG2, while KDM4D, USP34, and VDR were significantly upregulated in gastric cancer tissues compared with normal controls." (PMID 42195053, 2026).
glioblastoma (1 paper, 2024). The most malignant astrocytic tumor (WHO grade IV). "Furthermore, in glioma stem cells (GSC), Pin1 undergoes deubiquitination and stabilization via the action of USP34, which is instrumental in facilitating glioblastoma (GBM) initiation, progression, and therapeutic resistance." (PMID 39624096, 2024).
hepatocellular carcinoma (1 paper, 2025). A malignant tumor that arises from hepatocytes. "The function and mechanism of ubiquitin-specific protease 34 (USP34) in hepatocellular carcinoma (HCC) were explored to provide new molecular targets for treating HCC." (PMID 40260316, 2025).
Hodgkinlymphoma (1 paper, 2019). "In particular, recurrent gain/amplificationof the 2p15-p16.1 locus, where REL, BCL11A, PAPOLG,PUS10, and USP34 genes reside, is a common observationin different lymphoma types including classical Hodgkinlymphoma and transformedfollicular lymphoma." (PMID 31410080, 2019).
Hypertension (1 paper, 2024). The presence of chronic increased pressure in the systemic arterial system. "Two of the recurrent AF genes also code for functions directly or indirectly linked to AF (CASQ2 and GOSR2), and some genes indicate a possible indirect link related to comorbidities, e.g., hypertension or malignancy (PPFIA4, USP34, WIPF1, SPATS2L, CAND2, and AOPEP)." (PMID 38725839, 2024).
Intellectual disability (1 paper, 2021). "Haploinsufficiency of USP34 and XPO1 has been postulated as a mechanism of disease in a patient with mild intellectual disability and cranio-facial dysmorphisms." (PMID 34321086, 2021).
medulloblastoma (1 paper, 2021). A malignant, invasive embryonal neoplasm arising from the cerebellum. "SOX2 co-immunoprecipitation identified a number of interacting proteins in medulloblastomas cells, including Usp9x and Usp34." (PMID 33613844, 2021). "In addition, SOX2 interacts with deubiquitinases Usp34 and Usp9x which can lead to SOX2 stabilization in medulloblastoma cells and was also shown in embryonic stem cells." (PMID 33613844, 2021).
melanoma (1 paper, 2021). A malignant, usually aggressive tumor composed of atypical, neoplastic melanocytes. "Usp9x KD but not Usp34 KD reduced SOX2 levels in both BRAF mutant A375, SK-Mel28, and NRAS-mutant SK-Mel147 melanoma cell lines." (PMID 33613844, 2021).
microcephaly (1 paper, 2023). A congenital or acquired developmental disorder in which the circumference of the head is smaller than normal for the person's age and sex. "Our results delineate an intricate pattern of genotype − phenotype correlation where BCL11A emerges as the main gene for autistic behavior while USP34 and/or XPO1 haploinsufficiency are mainly associated with microcephaly, hearing loss and IUGR." (PMID 36807877, 2023). "In agreement with previous reports, our investigation showed that BCL11A is particularly involved in cortical and cerebellar anomalies, and autistic behavior whereas USP34/XPO1 deletions are more associated with corpus callosum anomalies, microcephaly, IUGR, and hearing loss." (PMID 36807877, 2023). "Penetrant deletions for microcephaly outlined two SROs; SRO1 (p: 0.25, 2/8) including the BCL11A (cp: 0.23) and PAPOLG (cp: 0.13) genes, and SRO2 (p: 0.55, 6/11) overlapping the USP34 (cp: 0.77) and XPO1 (cp: 0.18) genes." (PMID 36807877, 2023).
Neurodevelopmental delay (1 paper, 2023). "However, our probabilistic analysis greatly favors XPO1 over USP34 as candidate gene, at least for neurodevelopmental delay." (PMID 36807877, 2023).
ovary tumor (1 paper, 2017). "It has been reported that somatic variations of USP34 are related to ovary tumor." (PMID 28493913, 2017).
tumor (9 papers, 2012 to 2025). "The results showed that USP34 mRNA levels were upregulated in tumor tissues compared with normal tissues." (PMID 40260316, 2025). "Meanwhile, negligible change of SUMO2/3 staining was observed in tumor tissues after USP34 silencing." (PMID 38167292, 2024). "Immunofluorescent analyses of the resultant xenografts with the apoptotic marker cleaved caspase-3 and the cell proliferation marker Ki67 showed that silencing USP34 dramatically elevated apoptosis but inhibited proliferation of tumor cells." (PMID 38167292, 2024). "The mRNA expression levels of three key genes (USP34, C3 and MGP) based on TCGA tumor data were also determined, and the USP34 gene was highly expressed in the cancer cell lines included in the T-LBL and T-ALL datasets according to CCLE analysis." (PMID 37664545, 2023). "Through WGCNA and Lasso, we identified that NDUFA13, UQCR11, and USP34 involved in the infiltration of Th2 cells and Tcm in tumor tissues, and the expression of genes is related to the recurrence of patients." (PMID 31795990, 2019). "The expressions of HSP90B1, USP34 and HMGN2 were significantly negatively associated with tumour grade (p<0.001)." (PMID 22363530, 2012). "We then explored the role of USP34 in GBM tumor growth in mouse brains." (PMID 38167292, 2024). "Likewise, immunofluorescent analyses of the GSC-derived xenografts showed that whereas a substantial portion of cells in the control tumors had intensive SUMO1 staining, disruption of USP34 resulted in a remarkable reduction of SUMO1 signals in tumor tissues." (PMID 38167292, 2024). "Furthermore, immunofluorescent analyses of human GBM samples demonstrated that the majority (>80%) of tumor cells with SUMO1 staining had strong USP34 expression." (PMID 38167292, 2024). "The results showed that most USP34-positive tumor cells also had strong Pin1 staining." (PMID 38167292, 2024). "Nevertheless, our study clearly demonstrates the tumor supportive role of USP34 in GBMs." (PMID 38167292, 2024). "However, less than 50% of tumor cells with SUMO2/3 staining had USP34 signals." (PMID 38167292, 2024). "Meanwhile, the expression of USP34 in HCC patients’ tumor tissues and adjacent non-tumor tissues was consistent with the database." (PMID 40260316, 2025). "Patients receiving intensive chemotherapy of their NBT showed significantly reduced tumor tissue expression of USP24, USP34, MINDY2, USP8, JOSD1, USP52, and USP12 when compared to the observation group." (PMID 37892185, 2023). "All these results confirmed that the mRNA and protein levels of USP34 in tumor tissues were markedly higher than those in adjacent non-tumor tissues." (PMID 40260316, 2025). "Collectively, these data demonstrate that USP34 promotes GSC maintenance and GBM tumor growth." (PMID 38167292, 2024).
cancer (7 papers, 2020 to 2025). A tumor composed of atypical neoplastic, often pleomorphic cells that invade other tissues. "Previous studies have reported that USP34 is closely associated with the development and progression of human cancers." (PMID 40599863, 2025). "The ubiquitin-specific protease 34 (USP34) gene and its protein are closely related to development and progression of human cancers." (PMID 37664545, 2023). "In general, advanced cancers were more aggressive than early cancers, which may illustrate that USP34 was correlated with the malignancy of HCC." (PMID 40260316, 2025). "Last but not least, all the regulatory enzymes discovered in this study, including USP34, Pin1, Plk1, CDK1 and Ubc9, could be effective drug targets for combination therapies to treat GBMs and potentially other malignant tumors." (PMID 38167292, 2024).
infection (2 papers, 2014 to 2023). The state of being infected such as from the introduction of a foreign agent such as serum, vaccine, antigenic substance or organism. "Interestingly, however, ATR, USP9, and USP34 were largely unaffected over a prolonged time course of infection." (PMID 38140597, 2023). "This hypothesis is reinforced by the observation that in response to infection, USP34 differentially regulates AMP genes expression which may typically reflect differential activity at the level of NF-κB-containing complexes." (PMID 25027767, 2014). "However, the induction of Dpt expression was significantly compromised in Usp34-silenced flies, resulting in a 30 to 50% reduction of Dpt induction from 3 to 9 hours following infection by E. coli." (PMID 25027767, 2014). "Notably, certain binding proteins, such as ATR and USP34, remain undegraded during infection." (PMID 38140597, 2023). "Similarly as observed for Dpt, overexpressing USP34 significantly reduced Drs expression at 12 and 24 hours after infection with the non-pathogenic Gram-positive bacteria Micrococcus luteus." (PMID 25027767, 2014).
neurodevelopmental disorder (2 papers, 2023 to 2026). A behavioral and cognitive disorder with onset during the developmental period that involves impaired or aberrant development of intellectual, motor, or social functions. "On the contrary to BCL11A, albeit thousands of whole − exome or whole − genome sequencing studies on patients with neurodevelopmental disorders, no inactivating mutations in USP34 or in XPO1 genes have yet been reported in the literature." (PMID 36807877, 2023).
bacterial infections (1 paper, 2014). "In contrast, antimicrobial peptide gene induction upon bacterial infection was differentially modified in Usp34-silenced flies." (PMID 25027767, 2014). "Therefore, when overexpressed in vivo, USP2 and USP34 behave as negative regulators of the fly immune response to bacterial infections." (PMID 25027767, 2014).
USP34 also shares sentences with these, for which no sentence is quoted: Obesity (2 papers); adrenocortical carcinoma (1); autism spectrum disorder (1); B-cell lymphoma (1); cardiovascular diseases (1); cerebral malaria (1); chronic obstructive pulmonary disease (1); colon adenocarcinoma (1); dementia (1); follicular lymphoma (1); intrauterine growth restriction (1); lymphoma (1); migraine (1); osteoarthritis (1); osteoporosis (1); osteosarcoma (1); rectal adenocarcinoma (1); renal diseases (1); virus infection (1).